HNF1A (HNF1 homeobox A)
Diseases named in the same sentence as HNF1A in open-access papers (continued):
Sharing a sentence is not in itself a finding about the gene and the disease.
type 1 diabetes (30 papers, 2012 to 2025). "Whether the pathogenic HNF1A variants are associated with body mass in general has largely been ignored, although variant carriers have been leaner than individuals with type 1 diabetes and control individuals." (PMID 34951657, 2022). "The LipoPrint© system (Quantimetrix, USA) based on non-denaturing, linear polyacrylamide gel electrophoresis was used to separate and measure LDL and HDL subclasses in fresh-frozen serum samples from patients with mutations of glucokinase or HNF1A, type 1 diabetes (T1DM) and healthy controls." (PMID 24549415, 2014). "The risk of coronary heart disease appears to be greater than that seen in type 1 diabetes which appears paradoxical when one considers the elevated high-density lipoprotein levels observed in those with HNF1A mutations (traditionally considered cardioprotective)." (PMID 23766565, 2013). "Among 1021 Chinese individuals with non‐type 1 diabetes in the training dataset, 19 (1.9%) individuals carried pathogenic or likely pathogenic variants in GCK (n = 6), HNF1A (n = 9), HNF1B (n = 3), or HNF4A (n = 1) genes." (PMID 40966384, 2025). "In this report, we present the case of a diagnosis of HNF1A MODY in a black sub-Saharan African young adult previously diagnosed with type 1 diabetes and treated with multiple daily insulin injections." (PMID 39420387, 2024). "Further research is needed to evaluate the influence of glycemic control, other maternal exposures (including gestational versus type 1 diabetes), ethnicity/HNF1α genotype, and preeclampsia on fetal renal development and fat metabolism." (PMID 35812800, 2022). "Sensitivity was 97% and specificity 96% for discriminating HNF1A/4A MODY from type 1 diabetes, with an UCPCR cut-off point of 0.2 nmol/mmol." (PMID 32528556, 2020). "The level of 1,5-AG was lowest in type 1 diabetes and HNF1A MODY, 3.8 and 4.7 μg/ml, respectively, and highest (11.2 μg/ml) in GCK MODY." (PMID 30778899, 2019). "An hsCRP value of <0.4 mg/L has a sensitivity of 71% and specificity of 77% for diagnosing HNF1A (as opposed to type 2 diabetes) once type 1 diabetes and glucokinase mutations have been excluded." (PMID 23766565, 2013). "Because PSP/reg1A levels have been shown to be elevated in HNF1A-MODY as well as type 1 diabetes patients, this suggested that PSP/reg1A levels may be negatively regulated by HNF4A." (PMID 23803251, 2013). "We have reported on a case of HNF1A MODY in a female young adult living in a sub-Saharan African setting, who was misdiagnosed as having type 1 diabetes, and treated with multiple insulin injections." (PMID 39420387, 2024). "The serum lipid profiles of the GCK-MODY group (n = 50) were compared with those of the hepatocyte nuclear factor-1 alpha (HNF1A)-MODY group (n = 19), the type 1 diabetes (T1D) group (n = 50), and the type 2 diabetes (T2D) group (n = 54)." (PMID 36387841, 2022). "Individuals with type 1 diabetes had a median UCPCR < 0.02 nmol/mmol, compared to 1.72 nmol/mmol in HNF1A/4A patients." (PMID 32528556, 2020). "In accordance with previous findings, the lowest levels of hsCRP were seen in HNF1A-MODY, but there was significant overlap of hsCRP distribution among individuals with HNF1A-MODY, GCK-MODY, and type 1 diabetes." (PMID 32528556, 2020). "The other biomarker, 1,5-AG, had the lowest plasma concentration in type 1 diabetes, not in HNF1A MODY group." (PMID 30778899, 2019).
Insulin resistance (23 papers, 2010 to 2026). Increased resistance towards insulin, that is, diminished effectiveness of insulin in reducing blood glucose levels. "Similar to ANRIL, rs1169288 SNP of Hepatocyte Nuclear Factor 1 alpha (HNF1α) has been observed in young diabetic patients, and association with insulin resistance." (PMID 41379817, 2025). "Some studies have shown that a decreased expression of HNF1α increases the risk of fatty liver, which is closely related to insulin resistance." (PMID 35299962, 2022). "In contrast to T2DM, which is a relative insulin deficient state with the pathology attributed largely to insulin resistance, it is a defect in insulin secretion that is the principal pathology of both HNF1A-MODY mutation carriers and T1DM." (PMID 26110317, 2015). "One possible explanation of the underlying mechanism might be that a high-fat diet downregulates HNF1A gene expression in the pancreas and thereby might cause weight loss and improvement of insulin resistance." (PMID 32971836, 2020). "These three individuals had HNF1A, HNF1B, and GCK variants, respectively, and they exhibited phenotypes associated with insulin resistance, including high BMI, hypertension, dyslipidaemia, and elevated fasting C‐peptide levels." (PMID 40966384, 2025). "An impaired glucose tolerance and insulin resistance are associated with ACE2-knockout, and possibly, HNF1α plays a critical role." (PMID 36005626, 2022). "T2DM is characterised by insulin resistance and beta cell failure, whereas HNF1A-MODY patients have been shown to have normal insulin sensitivity." (PMID 24069322, 2013). "Under a hypocaloric and high-fat diet, carriers of the HNF1A rs7957197 T allele demonstrated a higher drop in weight loss and improved insulin resistance levels than non-carriers under the same diet." (PMID 35873425, 2022). "This targeted approach using gas-chromatography-mass spectrometry has also been applied to insulin resistance studies in vivo and an increase in phenylalanine metabolites was in agreement with the known regulation of the phenylalanine hydroxylase gene by Hnf1α." (PMID 24252331, 2013). "Marked insulin resistance and the associated dyslipidaemia are not clinical features of HNF1A-MODY carriers." (PMID 24069322, 2013). "Altered HNF-1α function could contribute to insulin resistance, a key feature of T2DM." (PMID 38481895, 2024). "Furthermore, a high-fat diet, an important causative factor of insulin resistance, downregulated GnT-IVa expression in the pancreas due to abnormal export of the key transcription factors forkhead box protein A2 (FOXA2) and hepatocyte nuclear factor 1-alpha (HNF1A) from the nuclei." (PMID 27136596, 2016). "This work established a physiologically relevant HNF1A-MODY model, identified early insulin resistance as a key mechanism triggering hormonal dysfunction, and revealed HNF1A's role in multi-organ pathophysiology beyond traditional β cell dysfunction." (PMID 42100870, 2026). "In conclusion, HNF1A-MODY carriers have significantly lower levels of sCD36, a marker which is known to cluster with insulin resistance and atherosclerotic plaque development." (PMID 24069322, 2013). "HNF1A-MODY is primarily a disorder resulting in beta-cell dysfunction, with mutation carriers lacking features of the metabolic syndrome such as insulin resistance, as opposed to the multifactorial aetiology synonymous with T2DM." (PMID 26110317, 2015). "Hence, our study explores the capacity of piperine to manage hyperglycemia by modulating HNF-1α and SREBP-1c expression in an HFD and sucrose-induced insulin resistance/T2DM using an in vivo experimental animal model and in vitro cell line (Chang liver cells) model." (PMID 38481895, 2024).
liver cancer (20 papers, 2011 to 2025). An epithelial or non-epithelial malignant neoplasm that arises from the liver. "High-throughput analysis of cancer cell genomes has established that hotspot mutations in HNF4α and HNF1α occur in a variety of human cancers, including liver cancer." (PMID 34771521, 2021). "High-throughput analysis of cancer cell genomes has identified a number of hotspot mutations in HNF1α and HNF4α in liver cancer." (PMID 34771521, 2021). "In this review, we summarized the possible mechanisms associated with HNF4α and HNF1α that regulate multiple oncogenic pathways in the liver and discussed the potential use of HNF4α as a therapeutic target for liver cancer." (PMID 34771521, 2021). "Well-known and robust HNF-1α relationship with lipid and glucose metabolism faces greater chances of metabolic repercussions in the backdrop of HNF-1α-inactivation-associated liver cancers." (PMID 31685031, 2019). "In conclusion, our study shows that HNF1α loss can lead to epithelial-mesenchymal transition in liver cancer cell lines, with E-cadherin repression, TGFβ1 overexpression and increased migration abilities." (PMID 21975049, 2011). "Previous ChIP-sequencing from the ENCODE project in HepG2 cells, a liver cancer cell line that expresses HNF1A, and from our group in UM5 cells found an HNF1A binding peak, which contains the HNF1A binding sequence, in the FGFR4 enhancer region found in the first intron of the FGFR4 locus." (PMID 40731412, 2025). "In addition, the loss of HNF4A reduced ApoB and HNF1A expression and promoted tumor growth, especially in liver cancer." (PMID 36213507, 2022). "Therefore, identifying pathogenic mutations of HNF1α and HNF4α has implications for liver cancer biology and drug targets for precision medicine." (PMID 34771521, 2021). "However, while the role of HNF1A in different cancers has recently been examined, only a few studies have demonstrated a critical link between HNF1A mutations and the development of liver cancer." (PMID 35327967, 2022). "Additionally, our group reported for the first time that HNF4A G79C, F83C, and M125I mutations are loss-of-function mutations found in liver cancer patients, leading to a reduction in HNF1A gene expression and concomitantly, an increased risk of HCC development." (PMID 35327967, 2022). "The results imply that the HNF1A mutations we identified in the POU domain are pathogenic mutations that strongly affect protein function and augment the risk of the initiation of liver cancer development." (PMID 35327967, 2022). "To evaluate the effects of these somatic mouse (Y122C, R229Q and V259F) and human HNF1A (Y122C and V259F) mutations in the POU domain, we examined the transcriptional activity of those mutants found in liver cancer patients." (PMID 35327967, 2022). "Here, we review recent findings pertaining to role of HNF1α and HNF4α in liver cancer, and their possible targeting for liver cancer treatment." (PMID 34771521, 2021). "It covers the molecular mechanisms of HNF1α and HNF4α dysregulation and also highlights the potential of HNF4α as a therapeutic target in liver cancer." (PMID 34771521, 2021). "In this review, we update current findings on the roles of HNF1α and HNF4α in liver cancer development and progression." (PMID 34771521, 2021). "For example, HNF1A, a liver-specific transcription factor, appears to have a strong excess of creation upon signature 12, which is specifically found in liver cancer." (PMID 31109337, 2019). "HNF-1α-regulated lipid and glucose metabolisms face greater chances of metabolic repercussions in the backdrop of liver cancers." (PMID 31685031, 2019). "RNA-Seq analysis observed a strong correlation between HNF4A expression and expression of its target genes, ApoB and HNF1A, in liver cancers." (PMID 29899848, 2018). "We selected 14 translated tumor-mutated alleles for validation using SRM, including three genes (i.e., HNF1A, FAH and SPTBN1) that have been causally related to liver cancer." (PMID 26631547, 2015).
liver cancer (continued). "Liver cancer cell lines in which HNF1α expression was inhibited by siRNA underwent an epithelial-mesenchymal transition and lost hepatocyte differentiation and epithelial phenotype." (PMID 21975049, 2011). "Overall, liver cancer cells transfected with HNF1α siRNA lost expression of epithelial and tight junction markers and over expressed proteins usually expressed in mesenchymal cells, defining an epithelial-mesenchymal transition in those cells." (PMID 21975049, 2011). "We assessed in vitro the role of HNF1α in the observed deregulations by inhibiting its endogenous expression in human liver cancer cell lines using small interfering RNA." (PMID 21975049, 2011). "HNF1α acts as an important liver-specific cis-acting element for FGL1, and downregulation of HNF1α might responsible for the inhibition of FGL1 transcription in liver cancer." (PMID 34975333, 2022). "For instance, PPARG and HNF1A, master regulators for adipogenesis and the hepatic cell fate respectively, are among the top TRGs for the adipose and the liver tissues respectively and are found to be implicated in NAFLD and steatosis associated liver cancer." (PMID 34270548, 2021). "Therefore, identifying a link between their loss-of-function mutations and the molecular mechanism for tumorigenesis will help to improve understanding of how HNF4α and HNF1α function in liver cancer." (PMID 34771521, 2021). "Given the high expression of HNF1A in liver tissue, this excess of new binding sites could result in some novel, functional binding sites in liver cancer." (PMID 31109337, 2019). "Another study reported that HNF1α inhibition in liver cancer cell lines caused the loss of cell–cell contacts and the development of migration structures with the upregulation of TGFB1, SNAIL, and SLUG, suggesting EMT is triggered by the loss of HNF1α expression." (PMID 34771521, 2021). "Therefore, we propose that HNF4A mutations G79C, F83C, and M125I are functional mutations found in liver cancers and that loss of HNF4A function, through its mutation, leads to a reduction in HNF1A and ApoB gene expression with a concomitant increased risk of liver tumorigenesis." (PMID 29899848, 2018). "In OS tissues, other lncRNAs are significantly upregulated and related with metastatic progression, such as HNF1A (HNF1 homeobox A)-AS1, BCAR4 (breast cancer anti-estrogen resistance 4) and HULC (highly upregulated in liver cancer RNA)." (PMID 34576322, 2021). "Based on RNA-seq analysis, ectopic expression of FOXA3, HNF1A, and HNF4A resulted in expression levels in iHeps that are comparable to those observed in liver cancer cell lines." (PMID 34302118, 2021). "Several studies have revealed that primary liver tumors, including benign liver adenomatosis and HCC, are clustered in HNF1A-DM families." (PMID 30155490, 2018). "Additionally, the knockdown of HNF4α led to substantial reductions in HNF1α and APOB, and RNA-seq data from liver cancer patients also showed that the expression of HNF4α, HNF1α, and APOB mRNA are significantly correlated." (PMID 34771521, 2021). "Finally, HNF1A and HNF4A have been described to prevent EMT in liver cancer." (PMID 30909444, 2019). "Interestingly, HNF-1α and HNF-4α are downregulated in inorganic arsenic-induced hepatic cancers." (PMID 31685031, 2019).
adenoma (19 papers, 2011 to 2025). A neoplasm arising from the epithelium. "The second common subtype is the HNF1A-inactivated adenomas, which carry mutations in the transcription factor HNF1A57, 63 and are associated with MODY." (PMID 39470338, 2024). "We next considered adenomas IV and VI together, both sharing a second mutation in HNF1A and clustering close with one another in the PCA and the hierarchical clustering." (PMID 39408812, 2024). "NEK1, in turn is predicted to be acted upon by HNF1A (p = 0.4), a TF involved synthesis of liver specific transcripts and whose absence predisposes to adenomas." (PMID 39102671, 2024). "The β-catenin–mutated adenomas, sonic hedgehog adenomas, and inflammatory adenomas have the highest risk of bleeding, while HNF1A adenomas have the least." (PMID 39470338, 2024). "HCA inactivated for HNF-1α (H-HCA) represents 30–40% of adenomas and is the least aggressive subtype with a low risk of complications." (PMID 33572120, 2021). "Overall, there were 19 (24%) hepatocyte nuclear factor (HNF)-1a-mutated (HHCAs), 37 (47%) inflammatory (IHCAs), 5 (6.5%) b-catenin-activated (bHCA), and 18 (22.5%) unclassified (UHCAs) adenomas." (PMID 32086574, 2020). "HNF1α gene was found mutated in 84% of cases of adenomas, including familial forms, and HNF1α protein levels were found significantly reduced in moderately- and poorly-differentiated tissues from HCCs." (PMID 28943628, 2015). "This work took advantage of both genomic and transcriptomic analyses of hepatic HNF1A-mutated adenoma samples to identify genotypic–phenotypic correlations and define a signature of dysregulated pathways and somatic variants occurring upon hepatocyte transformation." (PMID 39408812, 2024). "In addition the of environmental factor and germline HNF1A-mutations, others genetic features could predispose to the occurrence of HNF1A mutated adenomas." (PMID 23401783, 2013). "As a result, HNF1A inactivated adenomas accumulate lipids in tumour hepatocytes leading to a characteristic homogeneous steatotic phenotype at histology, without inflammatory infiltrates." (PMID 32464711, 2020). "The first molecular subgroup accounts for 30% to 40% of adenomas and is defined by a mutation inactivating HNF1A, a gene coding for Hepatocyte Nuclear Factor 1 Alpha." (PMID 32464711, 2020). "In this line, predisposing genetic factors like HNF1A germline mutation related to MODY3 diabetes and GNAS mosaic somatic mutations related to McCune Albright disease are strong risk factors of adenomas occurrence." (PMID 23401783, 2013). "However, cases of brown pigment deposition in adenoma cells have been reported as pigmented HCA in Eastern countries and Japan, and it is associated with the HNF-1α-inactivated and β-catenin-activated types, which signify malignant transformation." (PMID 32382834, 2020). "The majority of the tumors represented adenomas similar to those of HNF1α-mutated type, though no mutations or stains have been attempted so far." (PMID 25566190, 2014). "HNF1α-mutated adenomas are developed in normal livers and do not show fibrosis, so this aspect of TGFβ is irrelevant, but HNF1α and TGFβ are both involved in hepatic differentiation." (PMID 21975049, 2011).